ARID1A (AT-rich interaction domain 1A)
Diseases named in the same sentence as ARID1A in open-access papers (continued):
Sharing a sentence is not in itself a finding about the gene and the disease.
pancreatitis (1 paper, 2018). Inflammation of the pancreas. "To test if the ability of Arid1a suppression to accelerate Kras driven preneoplastic transformation is due to a defect in acinar regeneration, we challenged C-RIK-shArid1a or C-RIK-shRen mice with pancreatitis induced by the cholecystokinin analog caerulein." (PMID 30014851, 2018).
Parkinson disease (1 paper, 2022). A progressive degenerative disorder of the central nervous system characterized by loss of dopamine producing neurons in the substantia nigra and the presence of Lewy bodies in the substantia nigra and locus coeruleus. "Low expression of ARID1A is mostly linked to Parkinson's disease signaling system and oxidative signaling system." (PMID 35028302, 2022).
pericardial effusion (1 paper, 2022). Fluid collection within the pericardial sac, usually due to inflammation.
pilocytic astrocytoma (1 paper, 2018). Pilocytic astrocytoma is a rare subtype of low-grade glioma of the central nervous system characterized by a well circumscribed, often cystic, brain tumor with a discrete mural nodule and long, hair-like projections that extend from the neoplastic astrocytes. "Histologic examination showed pilocytic astrocytoma (PA) with anaplasia, and molecular characterization revealed FGFR1 duplication with additional variants of unknown significance in several genes (ARID1A, ARID1B, CHEK2, EPHA5, and MLL2)." (PMID 29610389, 2018).
plasma cell neoplasm (1 paper, 2025). A clonal proliferation of immunoglobulin-secreting plasma cells. "These somatic alterations have been implicated in various processes central to plasma cell neoplasms, from chromatin remodeling (ARID1A, KMT2D, and BCL7A) to oncogenic signaling (PTPN11, NUP214)." (PMID 41378284, 2025).
polycystic ovary syndrome (1 paper, 2021). A disorder that manifests as multiple cysts on the ovaries. "In line with our finding, a prior study discovered that ARID1A overexpression diminished ovarian granulosa cell proliferation but augmented cell apoptosis in polycystic ovary syndrome." (PMID 34586697, 2021).
prostatic sarcoma (1 paper, 2022). "In summary, we describe a rare case of primary prostatic sarcoma that shows undifferentiated spindle cell with focal rhabdoid morphology and harbors biallelic inactivation of ARID1A detected by NGS with complete loss of ARID1A expression by IHC." (PMID 35125107, 2022).
seminoma (1 paper, 2020). A radiosensitive malignant germ cell tumor found in the testis (especially undescended), and extragonadal sites (anterior mediastinum and pineal gland). "Furthermore, we deciphered the molecular consequences of an ARID1A deficiency in seminoma-like TCam-2 cells." (PMID 32272809, 2020). "Thus, ARID1A negatively influences expression of pluripotency factors, but in long-term culture seminoma cells (TCam-2) can counteract this effect." (PMID 32272809, 2020). "Furthermore, seminoma-like TCam-2 cells might not be an ideal model to study DNA methylation levels of ARID1A in seminomas, since TCam-2 harbor untypically high levels of DNA methylation." (PMID 32272809, 2020).
Septo-optic dysplasia (1 paper, 2022). Septooptic dysplasia (SOD) is a clinically heterogeneous disorder characterized by the classical triad of optic nerve hypoplasia, pituitary hormone abnormalities and midline brain defects. "The identification of causative variants in SHH and ARID1A further expands the phenotypic spectra associated with these genes and reveals novel pathways to explore in septo-optic dysplasia." (PMID 35885948, 2022). "The identification of causative variants in SHH and ARID1A further expands the phenotypic spectra associated with these genes and identifies novel pathways to explore in septo-optic dysplasia." (PMID 35885948, 2022).
serous ovarian cystadenocarcinoma (1 paper, 2023). "For example, cluster 1 is enriched in high‐grade serous ovarian cystadenocarcinoma (SOC) with consistent activation of ARID1A." (PMID 36688815, 2023).
small-bowel cancers (1 paper, 2021).
spinal chordoma (1 paper, 2021). A slow-growing malignant bone tumor arising from the remnants of the notochord and occurring in the spine. "Our analysis of 32 spinal chordomas identified alterations in LYST, PTEN, CDC27, and ARID1A at similar frequencies compared with their spinal chordoma cohort." (PMID 33543146, 2021).
spindle cell sarcoma (1 paper, 2022). A malignant mesenchymal neoplasm composed of spindle-shaped cells. "Herein, we report a rare case of primary prostatic undifferentiated spindle cell sarcoma with focal rhabdoid morphology, harboring biallelic inactivation of ARID1A detected by next-generation sequencing with complete loss of ARID1A expression by immunohistochemistry." (PMID 35125107, 2022). "Herein, we report a rare case of primary prostatic undifferentiated spindle cell sarcoma with focal rhabdoid morphology, harboring biallelic inactivation of ARID1A detected by next-generation sequencing (NGS) with complete loss of ARID1A expression by immunohistochemistry (IHC)." (PMID 35125107, 2022).
spindle cell tumor (1 paper, 2025). "In summary, we reported the first case of primary pancreas NTRK-rearranged spindle cell tumor with a special sclerosing epithelioid fibrosarcoma pattern harboring EVT6::NTRK3 gene fusions, CDKN2A/2B homozygous deletion, and ARID1A mutation." (PMID 40548109, 2025).
Strabismus (1 paper, 2021). A misalignment of the eyes so that the visual axes deviate from bifoveal fixation. "Sparse scalp hair (8/15, 53%), hypoplasia of the distal phalanx (8/15, 53%), and strabismus (8/15, 53%) were the most common phenotypes reported in individuals with variants in ARID1A." (PMID 34205270, 2021).
suppressor tumors (1 paper, 2021).
T-cell lymphoma (1 paper, 2021). "For T-cell lymphoma six genes are found in cosmic (JAK1, PLCG1, FYN, ARID1A, EP300, and MAP3K1), and 13 are known oncogenes." (PMID 34570764, 2021).
Thrombocytosis (1 paper, 2026). Increased numbers of platelets in the peripheral blood. "Early Relapse (≤6 months) was primarily driven by higher stage (II–IV), positive peritoneal cytology, thrombocytosis, grade-3 endometrioid histology (G3), deep myometrial invasion, and ARID1A loss, with elevated CA125 providing additional risk." (PMID 41536692, 2026). "Key predictors included ARID1A loss, elevated CA125, thrombocytosis, and p16 expression among key predictors of relapse; while shared high-risk features across models were advanced stage, deep myometrial invasion, elevated CA125, and positive cytology." (PMID 41536692, 2026). "SHAP-based interpretability provided transparent, class-specific insights into model predictions by highlighting key biomarkers and risk factors, such as ARID1A loss, elevated CA125, thrombocytosis, p16 expression, FIGO stage, LVSI, cytology, tumor size, and E-cadherin status." (PMID 41536692, 2026).
thymic adenocarcinoma (1 paper, 2021). "The thymic adenocarcinoma harbored many mutations, including ARID1A c.421del(p.A141Pfs∗91), CTCF c.517G>T(p.G173∗), KMT2A c.2155A>C(p.S719R), BAP1 c.673G>A(p.D225N), ERBIN c.2900C>G(p.S967C), LZTR1 c.2216C>T(p.S739L), POLE c.52G>C(p.E18Q), and SRC c.1334A>C(p.K445T)." (PMID 33847622, 2021).
tumor predisposition syndromes (1 paper, 2022). "Although our data is clearly limited in this aspect, our findings suggest that NEC-like SMARCA4/ARID1A tumors may also occur in the context of tumor predisposition syndromes." (PMID 36443295, 2022).
vaginal squamous cell carcinoma (1 paper, 2021). A squamous cell carcinoma arising from the vagina. "A recent mouse model of ARID1A deletion paired with oncogenic KRASG12D developed invasive vaginal squamous cell carcinoma." (PMID 34941867, 2021).
Waldenström's Macroglobulinemia (1 paper, 2024). "Despite recurrent and activating mutations, including MYD88, CXCR4, ARID1A, KMT2D, and CD79B were identified, the genetic basis for Waldenström's Macroglobulinemia (WM) and the risk of progression of IgM MGUS to WM remain to be fully elucidated." (PMID 39711167, 2024).
Wilms tumor (1 paper, 2020). An embryonal neoplasm characterized by the presence of epithelial, mesenchymal, and blastema components. "No pathogenic PIK3CA mutations and three pathogenic ARID1A mutations (two of which were germline) were identified in a whole genome sequencing study of 117 cases of Wilms’ tumor." (PMID 32490123, 2020).
tumor (836 papers, 2010 to 2026). "Here, we demonstrate that ARID1A-deficient EC cells display a reprogrammed soluble secretome that alters tumor-stromal communication." (PMID 41957354, 2026). "Inhibition of JAK/STAT3 selectively inhibited the growth of ARID1A deficient endometria cancer cells in vitro and in a mouse xenograft tumor model." (PMID 41800254, 2026). "Elevated CXCL16 levels within the tumor niche also promote the conversion of stromal cells into cancer-associated fibroblasts (CAFs) in both preclinical models and patient samples of ARID1A-deficient EC." (PMID 41957354, 2026). "Numerous studies have demonstrated increased dependence on ATR signalling in ARID1A‐deficient tumours, along with synthetic‐lethal sensitivity to ATRis." (PMID 41537447, 2026). "In later stages of tumorigenesis, haploinsufficiency or complete loss-of-function ARID1A is linked to enhanced tumor development, particularly by promoting cell migration and metastasis." (PMID 41514650, 2025). "The correlation of increased ARID1A mutation frequency and dMMR phenotype has been described extensively in various tumor types." (PMID 41195266, 2025). "As an important tumor suppressor, it is essential to understand the mechanisms whereby ARID1A loss promotes various stages of cancer development." (PMID 40429787, 2025). "ARID1A (AT-rich interaction domain 1A) is a tumor-suppressor gene encoding a key component of the SWI/SNF chromatin remodeling complex, which plays a crucial role in regulating gene expression through the modification of chromatin structure." (PMID 40072110, 2025). "As tumors develop, mutational inactivation of ARID1A enables cancer cells to bypass growth limitations and adjust to an active tumor microenvironment." (PMID 41514650, 2025). "Since ARID1A has a known relationship with tumor immunity in adult cancers, we interrogated the effects of ARID1A loss on cytokine signaling in NB." (PMID 40082458, 2025). "ARID1A mutations are characterized by an increase in the density of tumor-infiltrating lymphocytes, prompting growing interest in studying type 1 immune responses associated with these mutations for immunotherapy." (PMID 40761291, 2025). "These ARID1A loss-of-function mutations resulted in reduced protein expression and impaired chromatin remodeling activity, and were strongly associated with tumor progression, distant metastases, and shorter overall survival." (PMID 40750787, 2025). "Tumors with ARID1A loss are more likely to have DNA repair deficiencies, which also correlate with tumor aggressiveness and higher recurrence rates." (PMID 40072110, 2025). "ARID1A, since it is a tumor suppressor, experiences weakened functions due to loss of SWI/SNF targeting to lineage-specific enhancers, leading to dedifferentiation and therapy resistance." (PMID 41514650, 2025). "Another study measured cell death between ARID1A-expressing and -deficient tumor xenografts when treated with a combination of a PARP inhibitor and ionizing radiation." (PMID 40429787, 2025). "In our study, the CTNNB1, FBXW7, NOTCH2 mRNA as well as the ARID1A promoter hypermethylation biomarkers were associated with the HGSOC tumor stage, suggesting possible implications for the prognosis, despite our study lacking more in-depth prognosis data." (PMID 40002854, 2025). "Both complete loss and partial reduction of ARID1A expression correlated with more aggressive tumor behavior." (PMID 41001036, 2025). "The proportion of ARID1A protein loss was even higher as the tumor-node-metastasis stage advanced, up to 35.2%." (PMID 40369167, 2025). "Homozygous Arid1a loss dramatically accelerates prostate tumourigenesis, resulting in hyper-proliferative and undifferentiated tumours with a reduced and disorganised stroma." (PMID 39885328, 2025). "The behaviour resulting from haploinsufficiency of PTEN and ARID1A demonstrates how somatic mosaicism of tumour suppressors arises and can predispose to cancer initiation." (PMID 39920335, 2025).
tumor (continued). "Arid1a loss mediated tumour formation in the mouse involved both the anterior and dorsolateral lobes, a key distinction from Pten-loss driven tumours which tend to be limited to the anterior lobes." (PMID 39885328, 2025). "Current research suggests that in chronic tumor models, ARID1A loss enhances effector T cell function and improves the persistence of anti-tumor immunity." (PMID 40342423, 2025). "The decreased proliferation upon ARID1A depletion is tumor‐suppressive, yet ARID1A is frequently mutated in early lesions already." (PMID 40170512, 2025). "To determine the significant factors related to the clinical course of GC, we analyzed potential associations between the expression of ARID1A, miR-129-5p and miR-3613-3p in tumor tissues of GC patients and their clinical and pathological characteristics." (PMID 39796161, 2025). "Here, we identify that a core driver of the cold tumor phenotype in NB is ARID1A loss, and thus, we interrogate ARID1A dependent differences in immune signaling using human NB cells." (PMID 40082458, 2025). "Mutations in ARID1A lead to DNA repair defects and transcriptional dysregulation, contributing to tumor progression." (PMID 40281353, 2025). "Implication in EAC-TME: (i) higher amounts of T cell levels are implicated in the tumor escape phenomenon; (ii) ARID1A deficiency is also implicated in fatty acid lipid metabolism, which can also be modulated for EAC treatment." (PMID 41369383, 2025). "ARID1A loss in tumor cells induces R-loops, which give rise to cytosolic DNA species that activate STING-type I IFN signaling, inducing an ARID1A–IFN gene expression signature that promotes anti-tumor immunity." (PMID 40699783, 2025). "Several large‐scale human cancer studies suggest that hemizygous loss of ARID1A is sufficient to drive tumour development in multiple cancers." (PMID 40621620, 2025). "Conversely, from the tumor microenvironment perspective, ARID1A mutations shape an inflamed (hot) tumor phenotype, thereby enhancing sensitivity to immunotherapy." (PMID 40406134, 2025). "These factors are commonly linked to a tumor’s ability to metastasize and suggest that the loss of ARID1A increases EMT and enhances metastatic potential." (PMID 40429787, 2025). "Homozygous loss of Arid1a resulted in epithelial-dense tumours involving both anterior and dorsolateral lobes, contrasting to tumour formation in the control Pb-Cre;Ptenfl/flArid1a+/+ mice being limited to the anterior lobes." (PMID 39885328, 2025). "Specifically, ARID1A acts as a tumor suppressor, and its loss exacerbates malignant progression by enhancing tumor cell invasiveness and metastatic potential." (PMID 41001036, 2025). "Another study found that point mutations were enough to significantly increase tumor size in cells with limited ARID1A expression in the nucleus." (PMID 40429787, 2025). "By investigating ARID1A-deficient resected tumors after RT/CHKi treatment, we found that tumor PD-L1 expression was also increased, which is another hallmark of the ICB response." (PMID 40750787, 2025). "This determines the potential molecular mechanism underlying the anti‐tumour immunity and immunotherapeutic response observed clinically in ARID1A mutant cells." (PMID 39779467, 2025). "In total, this supported our initial findings seen in the Xena and TARGET tumor samples but also provided key insight into which areas of the IFNγ signaling pathway can change upon ARID1A loss." (PMID 40082458, 2025). "Both ARID1A and miR-3613-3p were associated with the primary tumor size (T in the TNM classification)." (PMID 39796161, 2025). "The loss of ARID1A function appears to contribute to enhanced invasiveness and metastatic protein by promoting changes in the tumor microenvironment and facilitating the acquisition of aggressive traits." (PMID 39941707, 2025). "Clinically, loss of ARID1A expression correlates with larger tumor sizes, deeper invasion, lymph node metastases and poor prognosis in GC patients." (PMID 39796161, 2025).